BRD7 (bromodomain containing 7)
Diseases named in the same sentence as BRD7 in open-access papers (continued):
Sharing a sentence is not in itself a finding about the gene and the disease.
cancer (48 papers, 2012 to 2025). A tumor composed of atypical neoplastic, often pleomorphic cells that invade other tissues. "For instance, PBRM1, ARID2, and BRD7, which encode subunits uniquely expressed by the pBAF complex, have been found to be mutated in approximately 1%–8% of human cancers." (PMID 41387924, 2025). "Another group of accessory factors mutated at high frequencies in cancer are bromodomain-containing proteins BRD7, BRD9, and PBRM1." (PMID 36605718, 2022). "In our study, there was no pathogenic mutation detected in any of the 40 TNBC patients, excluding a prominent role of BRD7 in the genetic predisposition to this cancer." (PMID 23110154, 2012). "Moreover, BRD7 deficiency sensitizes cancer cells to PARP inhibition." (PMID 33101843, 2020). "Drugs with higher potency and varying selectivity for either BRD9 and/or BRD7 have since been developed and tested for their anti-cancer effects." (PMID 38390898, 2024). "These promising findings on these novel BRD7-selective inhibitors deserve further exploration in other cancer types and in mouse models." (PMID 38390898, 2024). "miR-410 negatively regulates Bcl2 antagonist killer 1 (BAK1), Centrin 3 (CETN3) and Bromodomain containing protein 7 (BRD7) to promote other cancers." (PMID 38201476, 2023). "Recently, PROTACS targeting C-MYC, BET, androgen receptors, and BRD7 have effectively killed cancer cells." (PMID 36902170, 2023). "Consequently, BRD7 plays crucial roles in many aspects of cellular processes, such as cell proliferation, apoptosis, differentiation, and glucose metabolism; and its abnormal expression is broadly associated with the development of many diseases, including cancers." (PMID 34109174, 2021). "BRD7 has recently been found to act as a tumor suppressor gene, and its expression is down-regulated in cancers like breast cancer, nasopharyngeal carcinoma, prostate cancer, and ovarian cancer." (PMID 34298819, 2021). "Here, we review the role of BRD7 in a variety of clinical conditions, with a focus on glucose metabolism and cancer." (PMID 32992509, 2020). "To evaluate the prevalence of PBAF complex mutations, we queried the pan-cancer TCGA atlas (n = 10,359) and analyzed all three genes in the complex (PBRM1, ARID2, and BRD7)." (PMID 32820162, 2020). "A bioinformatic study also suggests that the BRD7 gene is frequently deleted in a large set of human cancers." (PMID 32992509, 2020). "A number of mechanisms have been proposed by which BRD7 expression is downregulated in cancer: these include increased methylation of the BRD7 promoter, microRNA-mediated degradation of BRD7 mRNA, and increased ubiquitination of the BRD7 protein by E3 ligases." (PMID 32992509, 2020). "Although the role of BRD7 in cancer has been extensively studied, the biological function and involvement in human malignancies of its close homolog BRD9 has not yet been elucidated." (PMID 31000698, 2019). "Accumulating evidence indicates that the down-regulation of the BRD7 gene contributes to the development of multiple types of human cancer." (PMID 26919247, 2016). "Two important SWI/SNF complexes implicated in cancer are the BAF and PBAF complexes, which contain the mutually exclusive ARID1A or ARID1B subunits and PBRM1 or BRD7 subunits, respectively." (PMID 24622842, 2014). "Two cell lines, acute myeloid eosinophilic leukaemia (EOL-1) and malignant rhabdoid tumour (A-204), sensitive to BRD9 inhibition/degradation and dependent on an active BAF complex, were selected to study the impact of degrader-induced BRD7/9 degradation on the viability of cancer cells." (PMID 35702740, 2022).
cancer (continued). "Furthermore, BRD7 has been shown to inhibit cancer cell growth and metastasis by not only impairing the activity of the c-Myc/miR-141 transcriptional axis but also by downregulating PI3K/Akt-mediated survival signaling 16,17." (PMID 33531996, 2021). "Levels of BRD7 mRNA are decreased in serous ovarian cancer, especially in high-grade cancer." (PMID 32992509, 2020). "The role of BRD7 has been implicated in cancers however, not much is known about its function in glucose metabolism." (PMID 27444544, 2016). "Down-regulation of BRD7 has been demonstrated in multiple types of cancer." (PMID 26919247, 2016). "Accumulating studies have shown that BRD7 is involved in human cancers." (PMID 27444544, 2016). "However, it is unclear whether BRD9 or BRD7, or both, were responsible for TP-472 anti-cancer effects." (PMID 38390898, 2024). "Therefore, BRD7 may be a potential genetic or drug target for improving the efficacy of chemotherapeutic drugs targeting CHK1 in future cancer therapies." (PMID 37626049, 2023). "More importantly, a potent and selective inhibitor for BRD7 was reported recently, which provides a promising therapeutic option for BRD7-driven cancers, revealing that targeting the BRD7/c-Myc axis could be an attractive approach for the treatment of c-Myc-driven cancers." (PMID 34109174, 2021). "The depletion of BRD7 improves the response to the immune checkpoint and CHK1 inhibitors, suggesting that BRD7 is also a potential therapeutic target in some cancers." (PMID 38390898, 2024). "Accumulating evidence has revealed that BRD7 is involved in cell cycle arrest via regulation of Ras/Raf/MEK/ERK, Rb/E2F, and AKT signaling in tumorigenesis and cancer progression." (PMID 34109174, 2021). "For instance, PARP1 inhibition suppresses BRD7 PARylation and its ubiquitination degradation, sensitizing BRD7‐positive, rather than BRD7‐negative cancer cells to chemotherapeutic drugs." (PMID 36909172, 2023). "Further study showed that LDB2 could recruit the tumor suppressor protein BRD7 into the promoter of the tumor-promoting protein HEY1 and exert the anti-cancer effect." (PMID 36473369, 2023). "Moreover, BRD7 has also been identified as a p85a-interacting protein that attenuates PI3K signaling and maintains the homeostasis of cell growth in cancer cells." (PMID 33531996, 2021). "Much less is known about SWI/SNF subunits BRD7 and BRD9 when it comes to their roles in cancer." (PMID 34298819, 2021). "Of note, overexpression of BRD7 negatively regulates β-catenin in cancer cells and positively regulates β-catenin in non-cancerous cells." (PMID 32992509, 2020). "Thus, the opposing functionalities of the closely related BRD7 and BRD9 proteins, as well as in SMARCA2/4, highlights the importance of understanding the roles of specific bromodomain-containing proteins in cancer biology in order to effectively develop new therapeutic strategies." (PMID 34298819, 2021).
infection (3 papers, 2021 to 2024). The state of being infected such as from the introduction of a foreign agent such as serum, vaccine, antigenic substance or organism. "Thus, this T cell–specific Brd7-deleted mice allowed us to specifically analyze the role of BRD7 in CD8+ T cell responses during infection." (PMID 38954484, 2024). "Therefore, we reveal a novel mechanism by which EBV can regulate its infection state by coordinating with host BRD7 to target c-Myc." (PMID 36728436, 2023). "Likewise, to investigate the role of BRD7 in a secondary effector CD8+ T cell response, we used a 2-infection model in our study." (PMID 38954484, 2024). "Notably, treatment of A549 cells with siRNAs that target BRD9 or GLTSCR1, but not BRD7 or ARID2, led to a reproducible (although not statistically significant) reduction in the ability of IFN‐α2 to fully protect cells from infection with the IFN‐sensitive vesicular stomatitis virus (VSV) (Fig EV1C)." (PMID 34397140, 2021).
BRD7 also shares sentences with these, for which no sentence is quoted: non-small cell lung carcinoma (5 papers); autoimmune disorders (1); bone cancer (1); breast tumours (1); chronic lymphocytic leukemia (1); genetic generalized epilepsy (1); Immunodeficiency (1); influenza (1); liver cancer (1); lung diseases (1); mantle cell lymphoma (1); metastatic melanoma (1); ovarian tumors (1); rectal cancer (1); serous carcinoma (1); squamous cell carcinoma (1); steatosis (1); sterility (1); synovial sarcoma (1).